VSIG4 (V-set and immunoglobulin domain containing 4)
Description:
Phagocytic receptor, strong negative regulator of T-cell proliferation and IL2 production. Potent inhibitor of the alternative complement pathway convertases.
Synonyms: CRIg; Z39IG
Tractability: Antibody: UniProt predicts a signal peptide or a membrane-spanning region.
Gene: Protein-coding gene on chromosome X (66,021,738 to 66,040,125, reverse strand). Ensembl gene ENSG00000155659.
Subcellular location: Membrane
Subcellular location (Human Protein Atlas): Cytosol; Plasma membrane; Nucleoli
Gene Ontology:
Molecular function: complement component C3b binding; protein binding
Biological process: negative regulation of complement activation, alternative pathway; negative regulation of interleukin-2 production; negative regulation of T cell proliferation; negative regulation of macrophage activation
Cellular component: protein-containing complex; membrane
Homologues: Orthologues: chimpanzee VSIG4 (99% identical), macaque VSIG4 (94% identical), pig VSIG4 (80% identical), dog VSIG4 (79% identical), rabbit VSIG4 (77% identical), mouse Vsig4 (44% identical), rat Vsig4 (43% identical).
Diseases named in the same sentence as VSIG4 in open-access papers:
VSIG4 is named in the same sentence as 118 diseases in open-access papers, as found by Europe PMC text mining. Sharing a sentence is not in itself a finding about the gene and the disease. The quoted sentences say what the papers report.
glioma (17 papers, 2016 to 2026). A benign or malignant brain and spinal cord tumor that arises from glial cells (astrocytes, oligodendrocytes, ependymal cells). "Higher expression levels of RAB3A, SYP, CAMK2A, and GABRA1, as well as lower expression levels of TYROBP and VSIG4, in glioma patients were associated with improved OS and DFS." (PMID 36072978, 2022). "Rab18 and V-set and immunoglobulin domain-containing 4 (VSIG4) were reportedly implicated in the malignant progression of glioma." (PMID 33904378, 2021). "Studies have found that VSIG4 expression presented increases in glioma tissues, which was closely associated with the prognosis of glioma." (PMID 33904378, 2021). "VSIG4, a marker highly specific to macrophages, is expressed in various cancers including lung, ovarian, pancreatic, thyroid, and high-grade glioma, where it is linked to tumor progression, poor prognosis, and immunosuppression." (PMID 40539047, 2025). "However, recent studies reported that VSIG4 expression is involved in lung cancer development and associated with poor prognosis of high grade glioma." (PMID 28938542, 2017). "In addition, we compared triplet signatures with previously identified prognosis-associated biomarkers in glioma, such as VSIG4 and TRIM8." (PMID 26943771, 2016). "VSIG4 expression may be associated with cancer and inflammatory diseases, and its high expression affects the poor prognosis in patients with tumors such as glioma, ovarian cancer, and gastric cancer." (PMID 36387195, 2022). "Studies have revealed that VSIG4 is a poor prognostic factor in patients with high-grade glioma, gastric cancer, and ovarian cancer." (PMID 39920772, 2025). "The relationship between VSIG4 and poor prognosis has been confirmed in lung cancer, ovarian cancer, and glioma." (PMID 38846981, 2024). "High expression of VSIG4 was associated with poor prognosis of OS and PFS in high-grade glioma patients." (PMID 36072978, 2022). "We identified VSIG4 for immunotherapy response in patients with glioma, demonstrating utility for immunotherapy research." (PMID 36072978, 2022). "To explore the roles of Rab18 and VSIG4 in glioma, we silenced Rab18 or overexpressed VSIG4 to detect the proliferation and apoptosis of cells, as well as the relationship between Rab18 and VSIG." (PMID 33904378, 2021). "The study lay a crucial foundation for the development of drugs targeting Rab18 or VSIG4, and provide a novel sight for understanding of the pathophysiology of glioma." (PMID 33904378, 2021). "Our study first confirmed that there existed an interaction between Rab18 and VSIG4 in glioma cells." (PMID 33904378, 2021). "Upregulation of CX43 by VSIG4 induction also accounted for the facilitation of glioma cells resistant to temozolomide (TMZ)." (PMID 33904378, 2021). "Similarly, the overexpression of V-set and immunoglobulin domain containing 4 (VSIG4) induces EMT in glioma cells, significantly promoting invasion and migration." (PMID 41141394, 2026). "VSIG4 was also reported as an independent prognostic factor in multiple myeloma and glioma." (PMID 39920772, 2025). "For example, overexpression of VSIG4 in high-grade gliomas, gastric cancer, and multiple myeloma have been associated with poor prognosis, while low VSIG4 expression in tumor tissue was related to poor prognosis in patients with HBV-associated hepatocellular carcinoma." (PMID 38169731, 2023). "VSIG4 is highly expressed and correlated with the poor prognosis of high-grade glioma patients." (PMID 39280892, 2022). "Let-7g-5p could inhibit epithelial-mesenchymal transition of glioblastoma by targeting VSIG4, which was consistent with the reduction of the glioma stem cell (GSC) phenotype." (PMID 36072978, 2022). "Finally, Identification VSIG4 for immunotherapy response in patients with glioma demonstrating utility for immunotherapy research." (PMID 36072978, 2022).
glioma (continued). "Finally, the identification of VSIG4 for immunotherapy response in patients with glioma demonstrates utility for immunotherapy research." (PMID 36072978, 2022). "Based on these, we proposed that a possible interaction of Rab18 and VSIG4 could be involved in the progression of glioma." (PMID 33904378, 2021). "All in all, these findings suggest that targeting the interaction of Rab18 and VSIG4 could contribute to marked efficacy in glioma while provides novel sights for understanding the pathogenesis of glioma and developing new therapeutical methods." (PMID 33904378, 2021). "Targeting the interaction between Rab18 and VSIG4 may help exploit new therapies to enhance TMZ sensitivity for treating patients with glioma." (PMID 33904378, 2021). "VSIG4 was found to promote carcinogenesis by inhibiting cytotoxic T-lymphocyte activation and acted as an independent predictive factor for a shorter progression-free survival and overall survival in high-grade glioma patients." (PMID 31886185, 2019). "Finally, identification of VSIG4 for immunotherapy response in patients with glioma indicates that the VSIG4 signature may have the ability to predict the effect of immunotherapy in glioma." (PMID 36072978, 2022). "We identified six hub genes (RAB3A, TYROBP, SYP, CAMK2A, VSIG4, and GABRA1) that predicted the prognosis of glioma." (PMID 36072978, 2022). "After a series of database screening tests, we identified 11 modules during glioma progression, followed by six hub genes (RAB3A, TYROBP, SYP, CAMK2A, VSIG4, and GABRA1) that can predict the prognosis of glioma and were validated in glioma tissues by qRT-PCR." (PMID 36072978, 2022). "Six hub genes related to glioma diagnosis and prognosis were identified, including RAB3A, TYROBP, SYP, CAMK2A, VSIG4, and GABRA1." (PMID 36072978, 2022). "We provide evidence that Rab18 plays a role in proliferation and apoptosis of glioma cells, as well as the sensitivity for TMZ through interacting with VSIG4." (PMID 33904378, 2021). "The binding between VSIG4 and THBS1 protein facilitating the malignant progression of glioma cells." (PMID 41019041, 2025). "Therefore, it could be concluded that RAB3A, TYROBP, SYP, CAMK2A, VSIG4, and GABRA1 may play a critical role in glioma by regulating immune cells." (PMID 36072978, 2022). "For the VSIG4 peptide GSDPVTIFLR, a sensitivity of 71.4% and specificity of 90.0% can be estimated at a cut-off of 36.2 fmol/μg protein and TAAQNLYEK (APOC2) can discriminate PCNSL from glioma patients at a cut-off of 8.3 fmol/μg with a sensitivity and specificity of 84.6% and 77.7%, respectively." (PMID 32610669, 2020).
ovarian carcinoma (12 papers, 2020 to 2025). A malignant neoplasm originating from the surface ovarian epithelium. "VSIG4 expression is associated with poor prognosis in patients with high‐grade glioma, advanced gastric cancer, and ovarian cancer patients." (PMID 39494816, 2024). "Furthermore, high mRNA levels of VSIG4 were associated with poor survival in patients with ovarian cancer." (PMID 32780724, 2020). "In advanced-stage and recurrent ovarian cancer patients, soluble VSIG4 levels were significantly increased (p = 0.0244 and 0.0288, respectively)." (PMID 33987033, 2021). "Based on VSIG4 transcript levels from the RNA-Seq data in human ovarian cancer TAMs, cMAP analysis revealed that VSIG4hi and VSIG4lo human TAMs aligned closely with the gene expression patterns of mouse Tim-4+ and Tim-4– TAMs, respectively." (PMID 32780724, 2020). "In addition, the amount of CD274 showed no obvious increase in some cancers when compared with counterparts from healthy donors, especially those in PDAC, breast cancer, and ovarian cancer, indicating VSIG4+ TAMs is an unignorable subpopulation in the TME." (PMID 39920772, 2025). "Although VSIG4 expression is restricted in tissue-resident macrophages at a steady state, several studies have reported an upregulation of VSIG4 expression in lung cancer, breast cancer, ovarian cancer, and multiple myeloma (MM)." (PMID 36189222, 2022). "In addition, VSIG4 transcripts were highly correlated with the expression of the alternative macrophage marker CD163 in human ovarian cancer." (PMID 32780724, 2020). "In line with our FACS data, TAMs highly expressed VSIG4 transcripts in human ovarian cancer." (PMID 32780724, 2020). "Importantly, recent single cell RNA sequence data confirmed expression of CD16 (FCGR3A), CD206 (MRC1), CD163, and CRIg (VSIG4) in macrophages from both peritoneal fluid at steady state and ovarian cancer ascites." (PMID 37180125, 2023).
gastric cancer (9 papers, 2020 to 2025). A primary or metastatic malignant neoplasm involving the stomach. "VSIG4 expression is associated with poor prognosis in patients with progressive gastric cancer." (PMID 39910672, 2025). "Recent studies have shown that VSIG4 overexpression in advanced gastric cancer is independently and strongly associated with poor prognosis, which indicates its potential as an important prognostic indicator in advanced gastric cancer." (PMID 35292033, 2022). "VSIG4 positivity in patients with advanced gastric cancer is associated with an adverse prognosis, but the relationship between VSIG4 expression and colon cancer survival has not been observed." (PMID 39726813, 2024). "And CSF1R of CD8 + Tcell, CCL2, VSIG4 of M2 Macrophage, NRP1 of Th1, TGFB1 of Treg cell presented strong correction with PCOLCE expression in gastric cancer (P < 0.001; Cor value ≥ 0.40)." (PMID 33392251, 2020). "However, since VSIG4 is characterized as a macrophage-specific molecule, neither the expression nor function of VSIG4 in any types of malignancy except gastric cancer has been reported yet." (PMID 37097516, 2023).
lung carcinoma (9 papers, 2017 to 2025). "High expression of VSIG4 is correlated with poor prognosis of high-grade glioma, and its deficiency led to significantly inhibited growth of Lewis lung cancer cells (LLC) in mice." (PMID 36189222, 2022). "Although tumor growth in murine lung cancer was significantly suppressed in VSIG4-deficiency mice and VSIG4 blockade showed anti-tumor activity in fibrosarcoma, the exact role and mechanism of VSIG4+ TAMs in aggressive cancers remain unclear." (PMID 39920772, 2025). "Tumor-associated macrophage is the prominent component of lung cancer stroma and VSIG4 may play a cancer-promoting effect in lung carcinoma development." (PMID 33691689, 2021). "Moreover, macrophage-associated VSIG4 was demonstrated to facilitate lung carcinoma and multiple myeloma development, which provided a promising immunotherapeutic target and prognostic indicator." (PMID 31886185, 2019). "VSIG4 is upregulated in multiple types of cancer, such as hepatocellular carcinoma, lung cancer, glioblastoma, and testicular cancer and its high expression is associated with poor prognosis." (PMID 41150752, 2025). "Here, we observed that VSIG4 expression was upregulated in lungs of aged mice bearing spontaneous tumors and in an A549 lung carcinoma xenograft model." (PMID 32856419, 2020). "VSIG4 expression was also found to be elevated in other aging tissues (e.g., thymus) and was strongly induced in tumor‐adjacent stroma in cases of spontaneous and xenograft lung cancer models." (PMID 32856419, 2020).
diabetes (7 papers, 2017 to 2026). "Taking advantage of the Chromogranin A (CgA) knockout (CgA-KO) mouse as a model for healthy aging, we have identified Vsig4 (V-set and immunoglobulin domain containing 4) as the critical checkpoint gene in offsetting age-associated hypertension and diabetes." (PMID 36440192, 2022). "This study aims to elucidate the role of VSIG4 in the aging process of kidneys, particularly in diabetes." (PMID 42195288, 2026). "Our results indicate that high glucose and angiotensin II, a well-known mediator of renal disease progression in diabetes, stimulated VSIG4 and profibrotic marker expression in podocytes." (PMID 35888119, 2022). "We observed that the addition of cDDGS positively affects the expression of several genes that have been recently proposed as potential targets for the treatment of obesity, diabetes, cardiovascular disease, and Alzheimer’s disease (e.g., FASN, AACS, ALAS1, HMGCS1, and VSIG4)." (PMID 30509175, 2018).
glioblastoma (7 papers, 2021 to 2025). The most malignant astrocytic tumor (WHO grade IV). "VSIG4 is also overexpressed in a variety of malignancies, including non-small cell lung cancer and glioblastoma, and plays a potential tumorigenic role by regulating T-cell proliferation, migration and invasion." (PMID 41218386, 2025). "The highest VSIG4-expressing tumor types included glioblastoma, mesothelioma, NSCLC, and pancreatic adenocarcinoma." (PMID 38892347, 2024). "VSIG4 is highly expressed in several malignant tumors such as lung cancer and promotes EMT in glioblastoma." (PMID 35888119, 2022). "Overexpression of VSIG4 induced EMT and significantly promoted invasion and migration of glioblastoma cells." (PMID 35888119, 2022). "VSIG4 induced epithelial-mesenchymal transition (EMT) and significantly promoted invasion and migration in glioblastoma U-87 MG cells." (PMID 39280892, 2022). "In addition, it has been recently reported that VSIG4 overexpression promoted the epithelial-mesenchymal transition (EMT), invasion and migration of U87-MG glioblastoma cells, which hinted the probability that targeting VSIG4 could inhibit EMT." (PMID 33904378, 2021).
Insulin resistance (7 papers, 2017 to 2025). Increased resistance towards insulin, that is, diminished effectiveness of insulin in reducing blood glucose levels. "VSIG4 is associated with insulin resistance and the epithelial-mesenchymal transition of kidney tubular cells under hyperglycemia." (PMID 40813429, 2025). "Vsig4 also plays a crucial role in “healthy aging” by counteracting age-associated insulin resistance and hypertension." (PMID 36440192, 2022). "VSIG4 has a protective role in cardiovascular diseases and can alleviate age-related insulin resistance and hypertension." (PMID 40630963, 2025). "Here, the authors use a viral hepatitis model and a high-fat diet model of insulin resistance to show how VSIG4 inhibits inflammatory macrophage activation by modulating mitochondrial pyruvate metabolism." (PMID 29109438, 2017). "For instance, Vsig4−/− mice are more susceptible to develop HFD-induced obesity and insulin resistance." (PMID 29109438, 2017). "Recently, it has been shown that the VSIG4 gene, which was one of the most upregulated genes by cDDGS in our study, inhibits macrophage-mediated inflammation, high-fat diet-induced obesity, insulin resistance, severe fibrinogen formation in the liver, mitochondrial oxidation and ROS formation." (PMID 30509175, 2018).
Obesity (7 papers, 2017 to 2025). Accumulation of substantial excess body fat. "Concomitant with obesity-associated reduction in Vsig4 abundance, bacterial DNAs were significantly accumulated in both patients with obesity and obese mouse islets after treatment of obese mEVs." (PMID 35091566, 2022). "In this study, we have shown that loss of Vsig4+ macrophages results in the translocation of intestinal EVs and microbial DNA accumulation within β cells, triggering obesity-associated islet inflammation and β cell abnormalities." (PMID 35091566, 2022). "Loss of Vsig4+ macrophages leads to microbial DNA accumulation in β cells and subsequently obesity-associated islet abnormalities." (PMID 35091566, 2022). "However, roles of islet Vsig4+ macrophages in the communication between microbiota and β cells in pathogenesis of obesity-associated islet abnormalities are unknown." (PMID 35091566, 2022). "However, the roles of islet Vsig4+ macrophages in preventing the development of obesity-associated islet inflammation and β cell abnormalities are still unknown." (PMID 35091566, 2022). "Obesity can reduce the number of complement receptors on CRIg+ and Vsig4+ macrophages in the livers of humans and mice, impairing the body’s ability to clear circulating BEVs." (PMID 40621163, 2025). "There was remarkably decreased abundance of Vsig4+ macrophages in both obese mice and patients with obesity." (PMID 35091566, 2022). "By contrast, as a result of decreased Vsig4 expression, islets from individuals with obesity exhibited worse GSIS and cellular insulin content after treatment with obese mEVs." (PMID 35091566, 2022). "Obesity suppresses Vsig4/CRIg+ expression in Kupffer cells in the liver, facilitating accumulation of bacterial DNAs in host tissues." (PMID 36440192, 2022). "Based on our observation from the obese mEVs-treated lean Vsig4−/− or C3−/− mice, gut mEVs infiltration could be one of factors expanding the population of CD11c + islet macrophages in obesity." (PMID 35091566, 2022). "Vsig4+ macrophages in islets play a critical role in clearing intestinal mEVs from circulation, whereas a reduction in the population of these cells is observed in obesity." (PMID 35091566, 2022). "We examined whether VSIG4 expression was upregulated in response to changes in adipose tissue elicited by obesity." (PMID 32856419, 2020). "Interestingly, compared to lean islets, there was a marked reduction in the population of Vsig4+ cells in the islets of 12wks HFD WT mice and patients with T2DM/obesity." (PMID 35091566, 2022). "However, this study did not ascertain whether VSIG4 was upregulated in wild‐type mice in response to obesity‐induced dysfunction." (PMID 32856419, 2020). "Thus, while the presence of VSIG4 appears to play a role in promoting adipose tissue homeostasis during the onset of diet‐induced obesity, our data suggest that age, but not diet‐induced obesity, induces a significant accumulation of VSIG4‐positive ATMs in gWAT." (PMID 32856419, 2020).